MCL1 (MCL1 apoptosis regulator, BCL2 family member)
Diseases named in the same sentence as MCL1 in open-access papers (continued):
Sharing a sentence is not in itself a finding about the gene and the disease.
breast carcinoma (continued). "Due to the important roles of CDK9 in malignancies, we found that the CDK9 inhibitor, DRB, also induced apoptotic death through rapid depletion of Mcl-1 in MCF-7 breast cancer cells and exerted a protective effect." (PMID 37537243, 2023). "Nearly 36% of breast cancer cases among 3131 cancer specimens exhibited increased levels of Mcl-1 expression levels." (PMID 37537243, 2023). "Anisomycin induces apoptosis in cancers by a diversified mechanism, which can induce apoptosis in a variety of cancers, including kidney cancer, breast cancer and human glioma, by regulating the bcl-2, C-flip (L) and McL-1 pathways." (PMID 37325053, 2023). "Recent studies showed that mTOR-mediated resistance to PI3Kβ and Akt inhibitors in breast cancer cells can be reversed by inhibiting the protein levels of Mcl-1." (PMID 37259388, 2023). "Mcl-1 expression in breast cancer cells is down-regulated by BAY 61-3606, making cancer cells more susceptible to TRAIL-mediated apoptosis." (PMID 36980514, 2023). "The up-regulation of Mcl-1 is usually found across a wide type of cancers, including breast cancer, and correlates to poor clinical prognosis." (PMID 37896184, 2023). "The five antiapoptotic genes (BCL2, BCL2A1, BCL2L1, BCL2L2, and MCL1) are frequently overexpressed in ER-positive breast cancer cells, and these genes have been used as clinical biomarkers in the diagnosis of breast cancer." (PMID 36853387, 2023). "Our findings suggest that dual-targeted therapy by Mcl-1 nioplexes and TZ is a potential strategy for the future progress of breast cancer treatments in HER2 overexpression patients." (PMID 37896184, 2023). "In summary, DRB induced the apoptosis of human MCF-7 breast cancer cells by regulating Mcl-1 and Bcl-xL, and activating caspase family members in a time- and dose-dependent manners." (PMID 37537243, 2023). "HER2-overexpressing breast cancer has high Mcl-1 expression; therefore, it is a fascinating therapeutic target for HER2-positive breast cancer." (PMID 37896184, 2023). "Herein, we found that downregulation of Mcl-1 expression increased ER-positive breast cancer MCF-7 cell sensitivity to DRB treatment." (PMID 37537243, 2023). "The molecular interactions of hesperidin extracted from C. limetta with the Bcl-2, Bcl-W, myeloid cell leukemia 1 (MCL-1), and ERα receptors overexpressed in breast cancer were investigated." (PMID 36978836, 2023). "The overexpression of Mcl-1 is observed in gastric cancer, breast cancer, non-small cell lung cancer (NSCLC), AML and colon cancer cells." (PMID 37686541, 2023). "Genomic gain of chromosome 1q21.2, where MCL1 is located, is frequent across a range of tumor types and is particularly common in breast cancers." (PMID 35349392, 2022). "This defines MCL-1 as a target in stroma-influenced breast cancers, and advocates for a comprehensive investigation of the effects of its targeting in distinct cellular components, such as myofibroblastic CAFs, of these tumor ecosystems." (PMID 36104324, 2022). "Our findings underscore the usefulness of targeting MCL-1 in breast cancer ecosystems, not only to favor death of cancer cells but also to counteract the tumorigenic activation of fibroblasts with which they co-evolve." (PMID 36104324, 2022). "Many types of cancer such as prostate cancer, myeloid leukemia, breast cancer, glioblastoma display strong chemo resistance, which is supported by enhanced expression of multiple anti-apoptotic Bcl-2, Bcl-XL and Mcl-1 proteins." (PMID 36267274, 2022). "An antiapoptotic protein called Mcl-1 has been shown to be a significant predictor of breast cancer, and thus, Mcl-1 mRNA is a suitable target for breast cancer treatment." (PMID 36421127, 2022). "Numerous studies showed that tumor intrinsic deregulation of MCL-1 expression/activity promotes breast cancer progression and treatment resistance." (PMID 36104324, 2022).
breast carcinoma (continued). "As well as successfully inducing apoptosis in several models of hematological malignancies, subsets of breast cancer cells are sensitive to MCL-1-specific BH3-mimetics in vitro." (PMID 35349392, 2022). "We ourselves established that MCL-1 mRNA expression positively correlates with stromal score in publicly available expression datasets from luminal breast cancers." (PMID 36104324, 2022). "In ER+ breast cancer cells, Mcl-1 levels were induced upon treatment with the Bcl-2/Bcl-xL inhibitor ABT-263, whereas MCL1 silencing did not increase Bcl-2 or Bcl-xL, pointing to Mcl-1 as a driver of ABT-263 resistance." (PMID 35053443, 2022). "Inhibition of Mcl-1 effectively suppressed the metastatic potential of breast cancer cells and increased the overall efficacy of dasatinib." (PMID 36045907, 2022). "In the case of breast cancer, Mcl-1 inhibitors have shown promising activity in preclinical studies." (PMID 35053443, 2022). "It is now understood that MCL1 is frequently upregulated across a range of solid tumor types, including breast cancer." (PMID 35349392, 2022). "Breast cancer associated fibroblasts (bCAFs) are dependent upon MCL-1 for survival and through secretion of IL-6, bCAFs can induce upregulation of MCL1 mRNA and protein in luminal breast cancer cells to reduce sensitivity to BCL-2/XL inhibition." (PMID 35349392, 2022). "Together, our results provide preclinical data in support of Bcl-xL inhibition as a potential clinical strategy for radiosensitization of PIK3CA/PTEN wild-type breast cancers with low expression of Mcl-1." (PMID 36381235, 2022). "The selective Mcl-1 inhibitor VU661013 induced ER+ breast cancer cell apoptosis and inhibited tumor growth in vivo." (PMID 35053443, 2022). "Taken together, this makes MCL-1 an extremely attractive target for clinical evaluation in the context of breast cancer." (PMID 35349392, 2022). "On-target compounds specific to MCL-1 have demonstrated promising efficacy in preclinical models of breast cancer and show potential to enhance the anti-tumor effect of conventional therapies." (PMID 35349392, 2022). "MCL1 was significantly increased in breast cancer and lung adenocarcinoma, and CDK4 in colon adenocarcinoma." (PMID 35249548, 2022). "MCL-1 in particular is frequently overexpressed in many cancers, including breast cancers, and this was established to contribute to resistance to the cytotoxic effects of chemotherapy, radiotherapy and BH-3 mimetics selectively targeting other BCL-2 homologs." (PMID 36104324, 2022). "In a study of 428 treatment naïve breast cancers we observed a range of MCL-1 protein expression within all classical subtypes, and each subtype contained cases possessing high levels of MCL-1." (PMID 35349392, 2022). "Inhibition of ERK activity was shown to downregulate Mcl-1 levels and induce apoptosis in breast cancer cells." (PMID 35053443, 2022). "SRPK1 maintains RBM4 in the cytoplasm of breast cancer cells promoting preferential splicing of the anti-apoptotic myeloid leukaemia 1 (MCL-1) long isoform." (PMID 35583632, 2022). "Targets including BCL2, CDK4 and MCL1 were highly expressed in all tumors; MCL1 was significantly increased in breast cancer and lung adenocarcinoma and CDK4 in colon adenocarcinoma." (PMID 35249548, 2022). "In summary, we have identified Mcl-1 as a new combination partner for PI3K and AKT inhibitors in PTEN-deficient breast cancer." (PMID 36241868, 2022). "In our study, MFLX was found to increase the level of Mcl-1 protein in MDA-MB-231 breast cancer cells and activated the apoptotic signaling pathway." (PMID 36045272, 2022).
breast carcinoma (continued). "PI3K/mTOR signaling inhibition in PIK3CA-mutant and wild-type PIK3CA ER+ breast cancer cells reduced Mcl-1 levels." (PMID 35053443, 2022). "One of the key drivers of Mcl-1 upregulation in breast cancer cells is the activation of PI3K/mTOR signaling." (PMID 35053443, 2022). "Taken together, this indicates that MCL-1 inhibition can sensitize different breast cancer subtypes to a range of therapies, though it is likely that refined treatment strategies will be required to circumvent significant toxicity in normal tissues." (PMID 35349392, 2022). "The exposure of breast cancer cells to the drug in concentrations of 0.5 mM and 1.0 mM for 12 h increased the level of Mcl-1 protein by 66% and 89%, respectively, when compared to the control." (PMID 36045272, 2022). "We also established that in luminal breast cancers, MCL-1 expression in tumor cells is extrinsically favored by paracrine effects of bCAFs." (PMID 36104324, 2022). "It is relevant here to note that MCL-1 mRNA and protein expression levels are inhibited by anthracyclines, which are part of the chemotherapeutic cocktail used for breast cancer therapy." (PMID 36104324, 2022). "The 3nAGN-NSC had also induced Mcl-1 mRNA expression in MCF-7 human breast cancer cells at 8, 12, and 24 h." (PMID 35745769, 2022). "Recent work in our group suggests that a key function of MCL-1 in conferring stem-like behavior in breast cancer is through its canonical role within the BCL-2 family." (PMID 35349392, 2022). "The downregulation of Mcl-1 by siRNA has positive therapeutic benefits in breast cancer treatment since it reduces chemotherapy resistance and re-sensitizes tumors to cytotoxic drugs." (PMID 35745769, 2022). "CDK12 overexpression increases the phosphorylation of antiapoptotic proteins, including Survivin and MCL-1 and correlates with shorter overall survival in breast cancer, ovarian cancer and gastric cancer." (PMID 36248987, 2022). "Mcl-1 protein expression has been found to be elevated in breast cancers, with the highest levels determined in estrogen receptor-positive breast tumors." (PMID 35053443, 2022). "Mcl-1 also contributes to metastasis in breast cancer and resistance to proto-oncogene tyrosine-protein kinase Src (Src) inhibitor dasatinib." (PMID 36045907, 2022). "Collectively, our findings show that PI3K/AKT inhibitors prime breast cancer cells for Mcl-1 induced cell death and this is dependent on the ability to suppress AKT signalling and is independent of downstream mTORC1 signaling." (PMID 36241868, 2022). "Dramatically, when Mcl1 is conditionally ablated in the tumor epithelium of mice possessing allografted mammary tumors 8/9 tumors regressed, and in 4/9 cases this regression was complete and underpinned long-term tumor-free survival." (PMID 35349392, 2022). "These genetic studies reveal an exquisite dependency of MMTV-PyMT mammary tumors on MCL-1 for tumor maintenance and development." (PMID 35349392, 2022). "We therefore performed Western analysis of XBP‐1s and MCL‐1 in mammary tumors derived from the young and aged mice and found a significant increase in both XBP‐1s and MCL‐1 in the aged female‐derived samples." (PMID 36111352, 2022). "Genetically engineered mouse models (GEMM) allow investigation of tumor cells within an intact tumor microenvironment and have revealed a key role for MCL-1 in tumor development and maintenance of mammary cancer in vivo." (PMID 35349392, 2022). "Genetic deletion of Mcl1 in the mammary epithelium of MMTV-PyMT mice reveals an absolute requirement for MCL-1 in mammary tumor development and outgrowth." (PMID 35349392, 2022). "Despite these encouraging findings, pharmaceutical targeting of MCL-1 as a single agent has proved inefficient at restricting breast cancer growth in vivo when investigated with xenograft and PDX models in immunodeficient mice." (PMID 33785871, 2021).
breast carcinoma (continued). "Overexpression of Mcl-1 is manifested in various human malignancies, including breast cancer which contributes to cell survival and conventional therapeutic resistance." (PMID 33919902, 2021). "Our genetic models of acute Mcl1 deletion provide strong rationale for MCL-1 as a therapeutic target in established breast cancers." (PMID 33785871, 2021). "Recently OTS167 has been shown to inhibit the MELK-dependent phosphorylation of eIF4B in human breast cancer cell lines, which resulted in downregulation of anti-apoptotic factor myeloid cell leukemia 1 (MCL-1) expression." (PMID 33658483, 2021). "This is supported by tumoursphere assays, indicative of breast cancer stemness, where using either human or mouse tumour cells we found that MCL-1 inhibition with BH3-mimetic drugs completely recapitulated the effect of MCL-1 deletion." (PMID 33785871, 2021). "This has important implications for the future use of MCL-1-specific BH3-mimetic drugs in breast cancer treatment." (PMID 33785871, 2021). "Combined inhibition of BCL-2 and BCL-xL with ABT-263 had limited efficacy on breast cancer owing to high expression of MCL-1, while A-1210477 or VU661013 in combination ABT-263 has a synergistic effect." (PMID 33883020, 2021). "For instance, a recent study was published highlighting that the dependance of breast cancer on MCL1 expression was solely dependent on its apoptotic function." (PMID 34475520, 2021). "To further test the requirement for canonical MCL-1 function in human breast cancer stem cells we therefore used CRISPR/Cas9 editing to generate MCL1-, BAX/BAK- and MCL1/BAX/BAK-deficient versions of the human breast adenocarcinoma MDA-MB-231 cell line." (PMID 33785871, 2021). "This strongly supports the idea that the key function of MCL-1 in breast cancer is through its anti-apoptotic function." (PMID 33785871, 2021). "siRNA-mediated downregulation of Mcl-1 confers beneficial therapeutic effects toward breast cancer management." (PMID 33919902, 2021). "This revealed a strong genetic requirement for MCL-1 in breast cancer stem cells, which was pharmacologically confirmed using the MCL-1-specific BH3-mimetic drug A1210477." (PMID 33785871, 2021). "In breast cancer with high expression of MCL-1, S63845 displayed synergistic activity with docetaxel in TNBC and with trastuzumab or lapatinib in HER2-amplified breast cancer." (PMID 33883020, 2021). "Lastly, in breast cancer stem cells (CSCs), MCL1 is co-amplified with the MYC oncoprotein, which promotes oxidative phosphorylation that is independent of the canonical function in apoptotic regulation." (PMID 34475520, 2021). "MCL-1 is also highly expressed in most breast cancer subtypes, for example, triple-negative and HER2-amplified breast cancers, enabling tumour cell survival and chemoresistance." (PMID 34581776, 2021). "The ability of MCL-1 inhibitor S63845 to restrict human breast cancer stem cell growth was also negated in the absence of BAX/BAK, clearly illustrating the importance of canonical anti-apoptotic MCL-1 function in breast cancer stem cells." (PMID 33785871, 2021). "For these experiments, in addition to the MDA-MB-453 cells, we used the SKBR3 HER2-amplified breast cancer cell line, which is very sensitive to MCL-1 inhibition." (PMID 33589591, 2021). "Together with our experiments utilising mouse models, these data reveal that MCL-1 function in breast cancer stem cells in vitro and in tumour survival in vivo is due to its anti-apoptotic function that is targetable by BH3-mimetic drugs." (PMID 33785871, 2021). "As a role for MCL-1 has been suggested in breast cancer stem cells we investigated growth in tumourspheres, known to measure breast cancer stem cell activity." (PMID 33785871, 2021). "The deubiquitinase USP9X stabilizes MCL1, whose overexpression contributes to chemoresistance and poor prognosis in breast cancer." (PMID 34575114, 2021).
breast carcinoma (continued). "Together these data reveal that the pro-tumour role of MCL-1 in established breast cancer is predominantly due to its function in apoptosis regulation within the BCL-2 family." (PMID 33785871, 2021). "The anticancer effect of siRNA against anti-apoptotic genes, namely, Mcl-1, Bcl-2, and survivin, were first screened in breast cancer cell line MCF-7 and MDA-MB-231." (PMID 33919902, 2021). "The impact of acute homozygous Mcl1 deletion in fully developed mammary tumours was notable with regression occurring in almost all mice and long-term tumour-free survival achieved in 4/9 cases." (PMID 33785871, 2021). "We find that acute genetic deletion or pharmaceutical targeting of MCL-1 significantly impedes the growth of established MMTV-PyMT mammary tumours in vivo." (PMID 33785871, 2021). "Here, using genetic and pharmaceutical methods on mouse tumours in immune proficient mice, we find that targeting MCL-1 can have single-agent inhibitory effect on mammary tumour growth of established mammary tumours." (PMID 33785871, 2021). "Targeted MCL-1 blockade using RNAi also increased caspase-mediated cell death in ERα + breast cancer cells, resulting in sustained growth inhibition." (PMID 33308268, 2020). "Illustrating the utility of our approach, we identified a link between mitochondrial ubiquitin ligase MARCH5 in the response to MCL1 inhibitors, especially in breast cancer cell lines." (PMID 32627965, 2020). "Recent evidence suggests that suppression of MUC1, in turn, down‐regulates the anti‐apoptotic MCL1 protein in breast cancer cells." (PMID 32720467, 2020). "When the mTORC1 inhibitor RAD001 was added to ER + breast cancer cells, the MCL-1 protein levels decreased and cells were able to undergo apoptosis." (PMID 33308268, 2020). "For example, IL-6 increases the survival of breast cancer cells via ERK signaling that stabilizes MCL-1." (PMID 33114328, 2020). "This suggests that rationale derived combination therapies using the blockade of MCL-1 can induce cell death in all breast cancer subtypes in addition to single-agent MCL-1 inhibitor approaches in tumor clones with strong MCL-1 dependency." (PMID 33308268, 2020). "Quantification of RNA expression of the BCL-2 family proteins (BCL-2, MCL-1 and BCL-xL) in breast cancer cell lines and primary patient samples found higher MCL-1 transcripts compared to BCL-2 and BCL-xL." (PMID 33308268, 2020). "This revealed an unappreciated positive association between mitochondrial E3 ubiquitin–protein ligase MARCH5 dependency and sensitivity to MCL1 inhibitors in breast cancer cell lines." (PMID 32627965, 2020). "Increasing concentrations of the MCL-1 antagonist S63845 resulted in elevated levels of MCL-1 similar to what was observed when human breast cancer cell lines MDA-MB-231 and MDA-MB-468 were treated with S63845 for 48 h." (PMID 31735913, 2020). "We have already established that high levels of MCL-1 place it in close proximity to Cofilin in breast cancer models." (PMID 31735913, 2020). "As MCL-1 regulated the activity of Cofilin and the output of the SFKs in breast cancer cells, this led us to discover that drugs that antagonize MCL-1 can sensitize TNBC cells to dasatinib and suppress metastatic progression." (PMID 31735913, 2020). "However, dependencies on other pro-survival BCL-2 family members may exist depending on the type of cancer and treatment used, as recently reported data on breast cancer showed a positive correlation between not only MCL-1 but also BCL-2A1 expression and an inverse association with BCL-2 expression." (PMID 32913197, 2020). "In other studies, fucoidan decreased the expression of anti-apoptotic signals including Bcl-2, Bcl-XL, and MCL-1 in breast cancer." (PMID 31936539, 2020). "In contrast, MCL-1 is widely expressed in all breast cancers: estrogen-receptor-positive (ER +) breast cancers, HER2-amplified and triple negative breast cancers." (PMID 33308268, 2020).